SLC7A11 (solute carrier family 7 member 11)
Diseases named in the same sentence as SLC7A11 in open-access papers (continued):
Sharing a sentence is not in itself a finding about the gene and the disease.
prostate carcinoma (46 papers, 2017 to 2025). A carcinoma that arises from epithelial cells of the prostate gland. "(2023) revealed that androgen receptor variants in prostate cancer upregulate SLC7A11 and confer ferroptosis resistance, consistent with our identification of SLC7A11 as a central molecule in resistance regulation." (PMID 40416987, 2025). "Studies of the association of SLC7A11 with the development, progression, and treatment of prostate cancer are at an early stage." (PMID 41228362, 2025). "In this study, we constructed a diagnostic model using transcriptomic data from 837 prostate cancer samples and identified SLC7A11 as a key factor in tumor progression." (PMID 41330917, 2025). "In vitro ferroptosis in prostate cancer cells has been demonstrated to be triggered by downregulation of circDUSP22; the mechanism of action is associated with the suppression of the SLC7A11/GPX4 signaling pathway." (PMID 38994627, 2024). "This study aims to investigate the functional role of SE-mediated epigenetic regulation of SLC7A11 and its associated pathways in disulfidptosis within prostate cancer, by integrating pharmacological intervention, gene editing, and high-throughput omics approaches." (PMID 41330917, 2025). "Consequently, SLC7A11 may serve as a potential diagnostic and prognostic marker for prostate cancer, as well as an effective therapeutic target." (PMID 41228362, 2025). "It does so by increasing SLC7A11 expression through acting as a molecular sponge for miR-654-3p in prostate cancer cells." (PMID 41228362, 2025). "The glucose transporter inhibitor BAY-876 significantly suppresses tumor growth in SLC7A11-high prostate cancer models, highlighting a potential therapeutic vulnerability." (PMID 41330917, 2025). "Collectively, these findings demonstrate that deletion of FOXA1-SEs significantly inhibits SLC7A11-induced disulfidoptosis in prostate cancer cells." (PMID 41330917, 2025). "Taken together, these results suggest that circATP2C1 enhances proliferation, migration, and invasion by suppressing ferroptosis through sponging miR-654-3p to liberate SLC7A11 in prostate cancer cells." (PMID 41228362, 2025). "In summary, the discovery of the circATP2C1/miR-654-3p/SLC7A11 signaling pathway has enabled us to understand that circRNAs can regulate the proliferation and metastasis of prostate cancer cells by modulating ferroptosis." (PMID 41228362, 2025). "Our findings reveal that circATP2C1 increases SLC7A11 expression by sponging miR-654-3p, as miR-654-3p targets SLC7A11 in prostate cancer cells." (PMID 41228362, 2025). "In prostate cancer, SLC7A11 has been shown to sensitize tumors to ferroptosis inducers such as erastin and RSL3, which significantly inhibit tumor growth, especially when combined with second-generation antiandrogens like enzalutamide or abiraterone." (PMID 41330917, 2025). "Conversely, lncRNA OIP5-AS1 attenuates ferroptosis in prostate cancer cells by upregulating SLC7A11 expression through the miR-128-3p axis." (PMID 40191204, 2025). "OIP5-AS1 acts as a sponge for miR-128-3p, increasing SLC7A11 expression and inhibiting ferroptosis in prostate cancer." (PMID 40191204, 2025). "In summary, our findings suggest that GRh2 exposure induces ferroptosis in prostate cancer cells by repressing the SLC7A11/GPX4 pathway, leading to decreased cell viability." (PMID 40919139, 2025). "This section also analyzed the expression of FOXA1 and SLC7A11 across different prostate cancer cell lines." (PMID 41330917, 2025). "Under physiological conditions, SLC7A11 promotes the proliferation of prostate cancer cells (PC-3 and DU145) both in vitro and in vivo." (PMID 41330917, 2025). "Firstly, we evaluated the in vitro effects of SLC7A11 on the migratory capabilities and viability of prostate cancer cells." (PMID 41330917, 2025). "Flow cytometry assessed cell death in SLC7A11-overexpressing and knockout prostate cancer cells (PC-3 and DU145) under different culture conditions." (PMID 41330917, 2025).
prostate carcinoma (continued). "The modulation of prostate cancer cell proliferation was reversed by either overexpressing SLC7A11 or inhibiting miR-18a-5p in response to the silencing of circDUSP22." (PMID 38994627, 2024). "In the study, MUC1-C induced PBRM1 by E2F1-mediated activation at its promoters, allowing MUC1-C to form a complex with NRF2 and PBRM1 on the NRF2 target SLC7A11 to drive its transcription in human prostate cancer stem cells." (PMID 38358974, 2024). "Research on the involvement of SLC7A11 in the onset, progression, and therapeutic approaches for prostate cancer is still in its nascent stages." (PMID 38994627, 2024). "Previously reported oncogenic genes for prostate cancer, including SLC7A11 and pyruvate dehydrogenase kinase 1 (PDK1), were also suppressed after FUBP1 knockdown at both mRNA and protein levels in prostate cancer cells." (PMID 39146021, 2024). "For example, the lncRNA OIP5-AS1 suppresses ferroptosis and promotes tumor malignant progression in prostate cancer by activating the miR-128-3p/SLC7A11 pathway." (PMID 38385087, 2024). "The results suggest a close correlation between SLC7A11 and the initiation, progression, and unfavorable prognosis of prostate cancer patients." (PMID 38994627, 2024). "Nevertheless, more research is necessary to thoroughly understand the intricate regulation of SLC7A11 expression and transporter activity, as well as its unique function in controlling ferroptosis in prostate cancer cells." (PMID 38994627, 2024). "This study has mainly explored the regulatory function of circDUSP22 in modulating the expression of SLC7A11, thereby impacting ferroptosis in prostate cancer cells." (PMID 38994627, 2024). "This study highlights the role of the SNHG3/miR-152-3p/SLC7A11 axis in promoting prostate cancer progression by influencing methionine-dependence, underscoring the significance of miR-152-3p in inhibiting prostate cancer." (PMID 39606232, 2024). "Our study found that palbociclib affects the cellular iron and GSH content through TRIB3/SOX2/SLC7A11 signaling axis, disrupting the cellular redox balance and promoting ferroptosis in prostate cancer cells." (PMID 39362848, 2024). "What is known is that some of these gene products were shown to be implicated in prostate cancer progression, such as, for example, SLC7A5, SLC7A11, SLC11A1, SLC43A1 and SLC1A3." (PMID 36831650, 2023). "Recent studies found that SLC7A11 is highly expressed in non-small cell lung cancer, oral cancer, prostate cancer, malignant glioma and other cancers, which is closely related to cancer proliferation, invasion, metastasis and drug resistance." (PMID 37127605, 2023). "OTUB1 is overexpressed in human cancers and acts to suppress ferroptosis of prostate cancer by promoting SLC7A11 stability." (PMID 35864871, 2022). "For instance, lncRNA OIP5-AS1 boosts prostate cancer progression and resistance of cell iron death via miR-128-3p/SLC7A11 pathway." (PMID 35465835, 2022). "Bicalutamide and darolutamide but not apalutamide treatment significantly upregulated NR3C1 and SLC7A11 expression, demonstrating that AR antagonist-induced transcription in prostate cancer cells is not limited to a single AR antagonist." (PMID 31501863, 2019). "These in vivo findings support the critical role of SLC7A11 in promoting prostate cancer growth." (PMID 41330917, 2025). "Immunohistochemical analysis indicated that SLC7A11 expression was lowest in benign prostate (BP) samples, moderately elevated in prostate cancer samples with Gleason scores <7, and significantly increased in tumors with Gleason scores of 7 and >7, with the highest levels observed in the >7 group." (PMID 41330917, 2025). "Subsequently, whether miR-654-3p exerts effects on prostate cancer cells through SLC7A11 was investigated." (PMID 41228362, 2025).
prostate carcinoma (continued). "Furthermore, this study reveals that SLC7A11 is highly expressed in prostate cancer; the SLC7A11/GPX4 signaling pathway regulates cellular ferroptosis, thereby influencing prostate cancer proliferation and metastasis." (PMID 41228362, 2025). "Next, we investigated the role of SLC7A11 in prostate cancer cells." (PMID 41228362, 2025). "However, the regulatory mechanisms upstream of SLC7A11 in the initiation and advancement of prostate cancer are still unclear and require further investigation." (PMID 38994627, 2024). "Together, these results uncover an essential role of TRIB3/SOX2/SLC7A11 axis in palbociclib-induced ferroptosis, suggesting palbociclib a promising targeted therapy in combine with ferroptosis induction for the treatment of prostate cancer." (PMID 39362848, 2024). "Additionally, the overexpression of lncRNA PCAT1 promotes docetaxel resistance and suppresses ferroptosis in prostate cancer (PC-3) cells by upregulating c-Myc and solute carrier family 7 member 11 (SLC7A11)." (PMID 36835100, 2023). "In prostate cancer, researchers found that lncRNA SNHG3, lncRNA prostate cancer-associated transcript 1 (PCAT1) and lncRNA OIP5-AS1 could affect SLC7A11 mRNA expression through different regulatory mechanisms." (PMID 37127605, 2023). "Moreover, lncRNA OIP5-AS1 inhibits ferroptosis by targeting the miR-128-3p/SLC7A11 pathway in prostate cancer." (PMID 35338333, 2022). "Furthermore, lncRNA OIP5-AS1 inhibits ferroptosis by targeting the miR-128-3p/SLC7A11 pathway in prostate cancer." (PMID 36038548, 2022). "Nevertheless, circRNAs modulating SLC7A11 in prostate cancer remain unclear." (PMID 41228362, 2025). "Similarly, lncRNA OIP5-AS1 and SLC16A1-AS1 regulate ferroptosis through the miR-128-3p/SLC7A11 and miR-143-3p/SLC7A11 signaling axes in prostate cancer and kidney cancer, respectively, further confirming the extensive role of lncRNA in regulating ferroptosis in urinary system cancers." (PMID 39544949, 2024). "Among them, SLC7A11, OXSM, RPN1, and NDUFA11 showed higher expression levels in prostate cancer tissues compared to normal samples." (PMID 41330917, 2025). "In this study, overexpression of SLC7A11 significantly enhanced cysteine level in DU145 and PC-3 prostate cancer cells, whereas knockout led to a marked reduction in cysteine level." (PMID 41330917, 2025). "In prostate cancer, the inhibition of ferroptosis is facilitated by lncRNA OIP5-AS1 through its interaction with the miR-128-3p/SLC7A11 pathway." (PMID 40303288, 2025). "SLC7A11 and GPX4 are two key molecules that inhibit ferroptosis, and are highly expressed in prostate cancer and CRPC." (PMID 38705987, 2024). "Collectively, these findings suggest that palbociclib induces ferroptosis in prostate cancer cells by inhibiting the expression of TRIB3, thereby reducing SLC7A11 expression via SOX2." (PMID 39362848, 2024). "In this study, the c-Myc/miR-25-3p/SLC7A11 signaling axis has been found to be mediated by the Transcription Factor AP-2γ (TFAP2C), which can decrease ferroptosis in prostate cancer and promote chemoresistance." (PMID 38994627, 2024). "In addition to the downregulation of GPX4 and SLC7A11, the protein level of FSP1 was also reduced in evodiamine-treated prostate cancer cells." (PMID 40420092, 2025). "Except for directly targeting SLC7A11, miR-654-3p might suppress SLC7A11 transcription by targeting CREB1 in prostate cancer cells." (PMID 41228362, 2025). "Building on our previous research, further analysis of tumor progression within the training set revealed that RPN1 may act as a suppressor of prostate cancer progression, while OXSM, NDUFA11, and SLC7A11 appear to promote disease progression." (PMID 41330917, 2025).
prostate carcinoma (continued). "It has been found that SLC7A11 is involved in the development of resistance to docetaxel in prostate cancer, and the transcription factor AP-2γ (TFAP2C) inhibits ferroptosis in prostate cancer through the c-Myc/miR-25-3p/SLC7A11 signaling axis, which in turn promotes its resistance to chemotherapy." (PMID 41228362, 2025). "In order to confirm the hypothesis that circDUSP22 acts as a sponge for miR-18a-5p in controlling the expression of SLC7A11, a set of transfection experiments were performed on DU145 prostate cancer cells." (PMID 38994627, 2024). "Similarly, enzalutamide stimulated transcription of NR3C1 and SLC7A11 but not PSA or TMPRSS2, suggesting that enzalutamide-stimulated transcription is not limited to a single prostate cancer cell line." (PMID 31501863, 2019).
osteosarcoma (42 papers, 2016 to 2026). A usually aggressive malignant bone-forming mesenchymal neoplasm, predominantly affecting adolescents and young adults. "This process is particularly pronounced in cells with high expression of SLC7A11, such as osteosarcoma cells and nucleus pulposus cells from degenerated intervertebral discs." (PMID 41229417, 2025). "Ferroptosis regulation by miRNAs modulating GPX4 and SLC7A11 to either suppress or promote ferroptosis in hepatocellular carcinoma, osteosarcoma, and other cancers." (PMID 40403492, 2025). "Previous studies have shown that miR-26b-5p targets methionine adenosyltransferase 2A (MAT2A), leading to reduced GSH levels and promoting ferroptosis by blocking the STAT3/SLC7A11 pathway in osteosarcoma." (PMID 40403492, 2025). "For instance, lysine demethylase 4A (KDM4A) reduces the levels of H3K9me3 at the SLC7A11 promoter, leading to increased expression of SLC7A11 in osteosarcoma." (PMID 39595619, 2024). "In this study, we found that SLC7A11 is highly expressed in osteosarcoma cells, suggesting a high demand for cystine." (PMID 37460542, 2023). "For example, lysine demethylase 4A (KDM4A) protected against ferroptosis by decreasing H3K9me3 abundance at the SLC7A11 promoter to upregulate the expression of SLC7A11 in osteosarcoma." (PMID 37229485, 2023). "We demonstrated through WB that sulfasalazine directly inhibited SLC7A11 in osteosarcoma cells, and this effect was enhanced with increasing concentrations." (PMID 37460542, 2023). "Study has shown that controlling H3K9me3 demethylation in the promoter region of SLC7A11 can increase SLC7A11 expression, inhibit ferroptosis, and promote osteosarcoma cell lung metastasis." (PMID 37005430, 2023). "In summary, these results suggest that the SLC7A11 inhibitor sulfasalazine effectively suppressed the growth of osteosarcoma in vitro and in vivo, indicating the potential for clinical translation of sulfasalazine into osteosarcoma treatment." (PMID 37460542, 2023). "In conclusion, our results suggest a novel mechanism whereby super-enhancer-driven MLX rewires cysteine metabolism in osteosarcoma cells through SLC7A11 to cope with oxidative stress, which holds promise for therapeutic development in osteosarcoma." (PMID 37460542, 2023). "Pharmacological inhibition of SLC7A11 with the FDA-approved anti-inflammatory drug sulfasalazine leads to ferroptosis and impairs the growth of xenografted osteosarcoma cells, highlighting the potential of targeting SLC7A11 in osteosarcoma treatment." (PMID 37460542, 2023). "Previous studies have reported that disrupted SLC7A11 expression influences the survival and migration abilities of osteosarcoma cells." (PMID 37892851, 2023). "As a promoter of tumorigenesis, inhibition of SLC7A11 downregulates the progression of osteosarcoma." (PMID 37065475, 2023).